CRABP1 (cellular retinoic acid binding protein 1)
Diseases named in the same sentence as CRABP1 in open-access papers (continued):
Sharing a sentence is not in itself a finding about the gene and the disease.
neurodegenerative disease (2 papers, 2023 to 2025). A disorder of the central nervous system characterized by gradual and progressive loss of neural tissue and neurologic function. "Dysregulation or aberrant alterations in these processes have been implicated in various neurodegenerative diseases, providing avenues for the development of therapeutics that target CRABP1 signalosomes." (PMID 41154657, 2025). "This knowledge, together with emerging structural information, sheds lights on the strategies in designing next-generation CRABP1-signalosome-selective retinoids for the management of neurodegenerative diseases." (PMID 41154657, 2025). "Studies of CRABP1 knockout (CKO) mice revealed CRABP1 to be a new therapeutic target, especially for motor neuron (MN) degenerative diseases where CaMKII signaling in MN is critical." (PMID 36902410, 2023). "Importantly, in human studies, drastically reduced Crabp1 gene expression has been reported in neurodegenerative disease patients, including ALS and SMA patients; therefore, we prioritized the studies of CRABP1-binding ligands in the context of MN degeneration." (PMID 36902410, 2023). "Therefore, targeting the CRABP1–MAPK signalosome may provide a means to selectively reduce the secretion of pro-inflammatory exosomes, potentially mitigating neuroinflammation in certain neurodegenerative diseases." (PMID 41154657, 2025).
benign tumours (1 paper, 2018). "Our results confirm the potential of CRABP1 as a biomarker of DTC, based in a large number of DTC (n = 89) encompassing several subtypes – FTC, FVPTC and PTC, and controlled by a pool of normal thyroid tissues and of benign tumours – FTA." (PMID 29321030, 2018).
infection (1 paper, 2022). The state of being infected such as from the introduction of a foreign agent such as serum, vaccine, antigenic substance or organism. "Compared with the blank group, the expression level of CRABP1 in mice induced by H9N2 infection decreased at 3 and 5 days, while the expression level of CRABP2 increased at the same time." (PMID 35764970, 2022).
metabolic disorder (1 paper, 2022). "CRABP1 has also been implicated in HIV therapy associated with lipodystrophy and metabolic disorder." (PMID 35406141, 2022).
CRABP1 also shares sentences with these, for which no sentence is quoted: cardiomyopathy (2 papers); colorectal tumors (2); differentiated thyroid carcinoma (2); hepatocellular carcinoma (2); multiple sclerosis (2); pancreatic neuroendocrine tumor (2); adenocarcinoma (1); alopecia (1); Alzheimer disease (1); brain tumors (1); Chiari malformation type II (1); colitis (1); colorectal (1); colorectal adenoma (1); Crohn disease (1); depression disorder (1); diabetes (1); endocrine disorders (1); esophageal carcinoma (1); Esophageal Neoplasms (1); Ewing sarcoma (1); follicular carcinomas (1); gastritis (1); geographic atrophy (1); glioblastoma (1); glioma (1); head and neck squamous cell carcinoma (1); hearing loss (1); hypertriglyceridaemia (1); hypervitaminosis A (1).
A further 25 diseases each share a sentence with CRABP1 in 1 paper.